RNU6-28P (RNA, U6 small nuclear 28, pseudogene)
Synonyms: RNU6-28
Gene: Small nuclear RNA gene on chromosome 22 (31,479,383 to 31,479,489, reverse strand). Ensembl gene ENSG00000199248.
Homologues: Orthologues: pig U6 (94% identical), macaque U6 (88% identical), rat U6 (87% identical). Paralogues in human: RNU6-11P (94% identical), RNU6-37P (94% identical), RNU6-222P (93% identical), RNU6-29P (93% identical), RNU6-38P (93% identical), RNU6-1 (93% identical), RNU6-2 (93% identical), RNU6-39P (93% identical), RNU6-3P (93% identical), RNU6-4P (93% identical), RNU6-5P (93% identical), RNU6-6P (93% identical), and 1289 more.